CTNNB1 (catenin beta 1)
Diseases named in the same sentence as CTNNB1 in open-access papers (continued):
Sharing a sentence is not in itself a finding about the gene and the disease.
tumor (continued). "The polymorphism of CTNNB1 is associated with cancer risk, suggesting that it may affect the occurrence and development of tumors by regulating the role of neuroactive ligands in the tumor microenvironment." (PMID 40331986, 2025). "Similarly, RT-PCR for the CTNNB1 mutation was used in one out of two desmoid tumor samples." (PMID 39001377, 2024). "Below, we describe these two types of tumour metabolism as corresponding to the two classes cited above: a highly proliferative one, which would be merely glutaminolytic, and a less proliferative one, characterised by its production of Gln and its CTNNB1 mutation status." (PMID 38699532, 2024). "Moreover, β-catenin IHC testing of tumor sections may be inadequate as a surrogate marker of CTNNB1 gene mutations in LUAD." (PMID 37347751, 2023). "However, if EDAR signalling had only a simple and positive relationship with β-catenin activity, then it is difficult to explain the observed selection for somatic mutations in CTNNB1 that produce an activated β-catenin protein in tumours of the EdarTg951/951 line." (PMID 34916592, 2022). "In addition to these, Wnt/CTNNB1 mutation is a characteristic of immune rejection (cold tumor) and maybe a biomarker for predicting drug resistance of immunosuppressants at immune checkpoints in HCC." (PMID 35812745, 2022). "The binding of CTNNB1 with AP-1 transcription factors might be associated with tumor malignancy." (PMID 36457029, 2022). "It was proposed that the discrepancies in the mutation profiles show that CTNNB1 mutations may have molecular fingerprints determined by biological factors, such as tumor type and underlying genomic instability pathways, so-called transcriptional misregulation pathways." (PMID 34836311, 2021). "Interestingly, CTNNB1 exon 3 mutations were associated with higher risk of tumour relapse." (PMID 34420090, 2021). "Additionally, we aimed to analyse the potential correlation of LEF1 and beta-catenin IHC with CTNNB1 exon 3 hotspot mutation, and to identify morphological parameters that could be predictive of CTNNB1 mutation in these tumours." (PMID 34420090, 2021). "Furthermore, CTNNB1 mutation was observed more frequently in the larger-sized tumours." (PMID 33914771, 2021). "Mutations in CTNNB1 may lead to tumor proliferation and thus a poorer outcome." (PMID 34195081, 2021). "The presence of CTNNB1 mutational homozygosity in cancers at a specific site, like the colon, may suggest that oncogenic activation acts in concert with a loss of tissue-dependent tumour suppression." (PMID 33115416, 2020). "Thus, targeting Pygo2 in malignant tumors that harbor Ctnnb1 mutations may result in suppression of tumor formation and growth." (PMID 27811361, 2016). "Tumours in most groups were predominantly monoclonal, as indicated by the presence of one or two APC-truncating mutations or a single Ctnnb1 exon-3 mutation." (PMID 41339549, 2026). "Collectively, our findings demonstrate polyclonal tumor origins in chemical carcinogen‐induced tumorigenesis, with Ctnnb1 splicing‐mutant clones driving clonal expansion and malignant transformation in AAI‐treated Arid1aLKO mice." (PMID 41133886, 2026).
tumor (continued). "Applying these driver proportions to overall intestinal tumour counts revealed that, for example, KrasG12D priming resulted in 596-fold and 58-fold increases in the number of Ctnnb1- and Apc-driven tumours, respectively, relative to the control cohort." (PMID 41339549, 2026). "Transfection of ENKUR-overexpressing EC cells with CTNNB1 reversed the suppressive effects on tumor growth and invasion." (PMID 39990660, 2025). "Tumor cells in these two types frequently exhibit genetic alterations in WNT pathway genes, particularly involving mutations in CTNNB1." (PMID 39851951, 2025). "In terms of oncogenes, mutations in CTNNB1 are frequently observed in HCC and similarly lead to aberrant activation of the Wnt/β-catenin pathway, driving tumor development." (PMID 40765562, 2025). "Eight genes were differentially expressed at both the mRNA and protein levels, with ASCL1, EDNRB, INSM1, SOX11, SOX4, SOX8, and SIX1 showing reduced expression in tumor tissues, and CTNNB1 showing increased expression compared with para-cancer tissues." (PMID 40771813, 2025). "In contrast, the actual expression of activated CTNNB1 is difficult to distinguish visually due to both cytoplasmic and nuclear staining which is particularly true in lipid-rich tumours like ACC." (PMID 40130164, 2025). "Recently, Cai's work reported that CTNNB1 activates MMP9 to induce a suppressive tumour immune microenvironment." (PMID 40111059, 2025). "In parallel, tdTomato+ tumor cells in Wnt GOF samples displayed increased nuclear Ctnnb1 levels relative to tdTomato− stromal cells." (PMID 41063628, 2025). "Genetic analysis revealed a heterozygous CTNNB1 deletion in one tumor, whereas a heterozygous PTEN deletion in the other." (PMID 41152971, 2025). "In tumor samples, elevated expression of classical CTNNB1-dependent transcriptional WNT targets correlates with elevated CTNNB1 protein levels, suggesting that CTNNB1 stabilization is consistent with WNT-dependent transcriptional hyperactivation." (PMID 40240755, 2025). "Among the eight significant mutated genes, CDK12, CTNNB1, and MLH1 were tested in both tumor and blood, whereas CTCF, IGF1R, IKBKE, QKI, and TIPARP were only tested in tDNA." (PMID 40227722, 2025). "In our study, the CTNNB1, FBXW7, NOTCH2 mRNA as well as the ARID1A promoter hypermethylation biomarkers were associated with the HGSOC tumor stage, suggesting possible implications for the prognosis, despite our study lacking more in-depth prognosis data." (PMID 40002854, 2025). "Dual inhibition with curzerene (a GSTA1 inhibitor) and β-catenin-IN-2 (a CTNNB1 inhibitor) synergistically reinstates ferroptotic sensitivity, suppressing tumor growth in cell lines, patient-derived organoids, and xenograft models." (PMID 41140341, 2025). "This study signifies the important role of CTNNB1 in tumor progression after post-radiation exposure of the cancer cells." (PMID 41186627, 2025). "Mutant CTNNB1 leads to a significant reduction in T cell infiltration, resulting in a so-called “cold tumor” phenotype that is inherently resistant to ICIs." (PMID 40765562, 2025).
tumor (continued). "Several studies have shown a high rate of CTNNB1 mutations in HCC associated with hepatitis C virus (HCV) infection, with over 40% of tumours presenting mutations." (PMID 41142820, 2025). "Conversely, tumor-suppressive circRNAs such as circ-CTNNB1 inhibit Wnt signaling by sequestering miR-520h, which targets APC, which is a key negative regulator of β-catenin." (PMID 40649179, 2025). "The stemness genes highly expressed in the C0 subtype included CTNNB1, CD44, and KDM5B, while in the Normal tissue adjacent to neoplasm group, CTNNB1, CD44, and MYC were highly expressed." (PMID 40616092, 2025). "Combination of GSTA1 inhibitor (Curzerene) + CTNNB1 inhibitor (β-catenin-IN−2) synergistically reduces tumor growth in cells, organoids, and xenografts." (PMID 41140341, 2025). "Nearly half of HCCs are Wnt-active with mutations in CTNNB1 (encoding for β-catenin), AXIN1/2, or APC, and demonstrate heterogeneous and limited benefit to ICI due to an immune excluded tumor microenvironment." (PMID 40442146, 2025). "To verify the effect of CPEB4 on the expression of CTNNB1 in vivo, we employed a nude mouse xenograft tumor model." (PMID 40084246, 2025). "The reversion of CTNNB1 in OV511 is unique in that it occurs at the primary site in a treatment-naïve tumor." (PMID 41279090, 2025). "On the other hand, the “immune exclusion class” is characterized by T-cell exclusion from the tumour microenvironment (TME) and CTNNB1 mutations, resulting in resistance to ICI therapy." (PMID 41142820, 2025). "Here the authors show that inhibiting b-catenin with lipid nanoparticles encapsulating siRNA targeting CTNNB1 impairs tumor growth and promotes anti-tumor immunity in preclinical HCC models." (PMID 40442146, 2025). "CTNNB1 exon 3 mutations, present in 23.1% of HCC cases worldwide, are similarly more prevalent in HCV-related HCC (30.7%) than in HBV-related tumours (12.8%)." (PMID 40650279, 2025). "EZH2, AURKB, GPC3, CTNNB1, and TGFβ were significantly upregulated in tumor tissues, indicating their potential roles in tumor progression." (PMID 40766612, 2025). "FoundationOne next-generation sequencing of the tumor showed mutations in NRAS, CTNNB1, and SMAD4 with microsatellite stability and low tumor mutation burden." (PMID 41120769, 2025). "The aim of this study was to investigate if coactivation of LIN28A and the WNT pathway (by expression of a stabilized CTNNB1) in neural precursor cells affect brain development and are sufficient and necessary to initiate tumor formation." (PMID 40680886, 2025). "The best single biomarker separator of HGSOC from the benign tumor group was CTNNB1 gene expression (AUC = 0.97)." (PMID 40002854, 2025). "On average, CTNNB1 mutated tumors showed 33.3% of ROR2 positive cells, while only 13.3% of WT tumor cells showed ROR2 positivity." (PMID 41227323, 2025). "As WNT and CTNNB1 mutations are rare in ICC patients, it is most likely that β-catenin signaling is activated via the WNT ligands from the tumor microenvironment." (PMID 38926350, 2024). "This disengages MYH9 from the cytoskeleton and increases its nuclear levels in EOC cells, which facilitates the transcriptional regulation of CTNNB1 and activation of Wnt/β‐catenin signaling and thereby induces tumor stemness and platinum resistance." (PMID 39488790, 2024).
tumor (continued). "While over-expression of Myc and Ctnnb1 promoted tumorigenesis in mouse liver, knockdown of Mat2b largely repressed tumor formation." (PMID 39353892, 2024). "MYC, EZH2 and CTNNB1 were the primary stemness genes with high expression levels in C2 UBE2C+ tumour cells." (PMID 38894657, 2024). "In contrast, higher miR-17-92 levels shift their targeting from PTEN to oncogenes, including Ctnnb1 (β-catenin) through miR-18a, inhibiting tumor growth and metastasis." (PMID 38534736, 2024). "The primary goal is to target activated CTNNB1 pathways or CTNNB1 mutations to induce immune infiltration and/or to target highly expressed VEGF to induce vessel normalisation, thus improving tumour hypoxia and facilitating higher immune infiltration." (PMID 38760445, 2024). "Particularly, immunotherapies targeting neoantigens from oncogenic driver mutations such as CTNNB1, DDX3X, and SMARCA4 and TAAs which have possible implications in tumor progression such as NEUROG1 and PIK3R3 are attractive for a better outcome in patients." (PMID 39160595, 2024). "The seeding cells carrying the CTNNB1 mutations gain the proliferation advantage due to the hyperactivation of the WNT/β-catenin signaling pathway and they become tumor germinal centers." (PMID 39223689, 2024). "To validate the impact of the CTNNB1 mutation on the tumour microenvironment during chemoimmunotherapy, we further assessed the tumour immune infiltration status using evidence from CD8+ T cells and PD‐L1 staining in patients with the CTNNB1 mutation via mIF." (PMID 38685486, 2024). "High tumor expression of LHCGR and GNRHR in APAs with CTNNB1 (and GNA11/Q) mutations has been a rationale for the link between the disease onset and pregnancy, menopause, or puberty." (PMID 38505749, 2024). "The results of the analyses conducted for the TCGA cohort revealed a significantly higher mRNA expression of UBB, UBC, and CTNNB1 in tumor tissues compared to normal tissues (p < 0.0001 for all)." (PMID 38473264, 2024). "In contrast, the expression levels of UBB, UBC, and CTNNB1 in tumor versus normal tissues varied between the GEO cohorts, ranging from being unchanged to being slightly overexpressed or downregulated." (PMID 38473264, 2024). "One study analyzed the TCGA-LIHC cohort and found significantly downregulated immune activation and response pathway activity but significant upregulation of pathways related to immune depletion or promotion of tumor growth in CTNNB1-MUT patients." (PMID 38806553, 2024). "Key mutations in genes like WT1, CTNNB1, and WNT, for example, have been linked to the onset and progression of the tumor, as well as its response to treatment, thus providing new avenues for targeted therapy." (PMID 39062028, 2024). "The spectrum of mutations, copy number changes, mRNA, and protein expression profiles within these 2 histologically distinct tumor areas demonstrate molecular heterogeneity and suggest intratumoral clonal evolution of this hepatocellular CTNNB1-mutant lesion." (PMID 37903123, 2024). "In conclusion, LNP-CTNNB1 is efficacious as monotherapy and in combination with ICI in CTNNB1-mutated HCCs through impacting tumor cell intrinsic signaling and remodeling global immune surveillance, providing rationale for clinical investigations." (PMID 39711542, 2024). "The HB nodule carried the same variants CTNNB1 and RPS6KA3 but at a much lower VAF (~5%), suggesting the evolution of a tumor subclone." (PMID 37903123, 2024). "Nearly half of HCCs are Wnt-active with mutations in CTNNB1 (encoding for β-catenin), AXIN1/2, or APC, and demonstrate limited benefit to ICI due to an immune excluded tumor microenvironment." (PMID 39711542, 2024).
tumor (continued). "In contrast, high UMIS metastases displayed lower tumor cell CTNNB1 expression, more activated APCs, greater CD8+ T cell recruitment, and robust interferon signaling." (PMID 38627362, 2024). "WNT medulloblastoma is mainly dependent on mutations in the CTNNB1 gene and the tumor suppressor gene APC which are responsible for driving the expression of the WNT signaling pathway and promoting tumor progression." (PMID 39160595, 2024). "(G–H) ChIP-qPCR showing enrichment of HNF4α (G) and p-S133-CREB1 (H) at Ctnnb1 promoter in native colon tissues of WT (n= 3) mice, tumor tissues of ApcMin/+ (n= 3) mice, and Ctnnb1Δi.enh;ApcMin/+ (n= 3) mice." (PMID 39320349, 2024). "Continuous knockdown of PAF1 reduced tumor weight and size to less than 20%, which was a stronger effect than that observed for continuous knockdown of CTNNB1." (PMID 38182897, 2024). "CTNNB1-mutated HCC are defined at the molecular, histo-pathological and clinical levels as tumours with specific characteristics, which we aim to summarise herein." (PMID 39261716, 2024). "Three patients carried somatic pathogenic variants in the CTNNB1 gene, which have already been described in ACTs, while four patients exhibited marked IC2-LoM on tumor DNA." (PMID 39682154, 2024). "In particular, western diet in this model induces aberrant splicing that leads to the exclusion of Ctnnb1 exon 3 in a subset of DIAMOND tumours." (PMID 37907668, 2023). "Strikingly, we identified a Ctnnb1 transcript isoform excluding exon 3 in 60% (3 out of 5) of the sequenced DIAMOND tumours, where 25% of the Ctnnb1 reads mapped to this region displayed exon 3 skipping." (PMID 37907668, 2023). "Recent reports have demonstrated that similar activation of β-catenin, either via engineered deletions or CRISPR targeting of Ctnnb1 exon 3 in the liver, is sufficient to generate tumours in mice." (PMID 37907668, 2023). "In a previous study, we have identified that circ‐CTNNB1 interacts with protein and drives tumour progression through the activation of the Wnt/β‐catenin signalling pathway in gastric cancer." (PMID 36181462, 2023). "Aside from CTNNA1, CTNNA2, and CTNNB1, there was low expression of most catenins in the tumor samples (P < 0.001) compared with the controls." (PMID 37924160, 2023). "This is consistent with other studies conducted mainly in adult patients, in which CTNNB1 was altered in over 90% of tumor samples." (PMID 37733117, 2023). "Driver mutations in the Wnt pathway were enriched in STAS positive tumours, (q = 0.033, Fisher’s exact test, FDR adjusted), and the bulk tumour transcriptomic profiles showed higher CTNNB1 gene expression (P = 0.0076, linear mixed effect model, ANOVA)." (PMID 37045996, 2023). "As we measured β-catenin levels in isolated cells, we found higher activation of β-catenin and induction of Wnt target genes, including Ctnnb1, cMyc, and Ccnd1, in Nlrp12–/– tumor epithelial cells." (PMID 37581937, 2023). "Transcription factors (TFs) associated with tumor metastasis and progression, such as MITF, MYC, and CTNNB1, showed high transcription activity in the MYC+MEL subcluster." (PMID 38065972, 2023). "The Ctnnb1 deletion clearly shifted the tumor transdifferentiation into SCC, with a notable decrease of ADC number." (PMID 36627278, 2023). "A four-gene panel consisting of ARID1A, CTNNB1, FBXW7 and PPP2R1A was used to investigate mutations in gynaecologic tumour tissue." (PMID 36982928, 2023). "iCluster1 tumours exhibited features such as higher tumour grade and presence of macrovascular invasion, a low frequency of CDKN2A silencing and CTNNB1 gene and TERT promoter mutations compared to iCuster2 and iCluster3." (PMID 36707636, 2023).